DGKG (diacylglycerol kinase gamma)
Description:
Diacylglycerol kinase that converts diacylglycerol/DAG into phosphatidic acid/phosphatidate/PA and regulates the respective levels of these two bioactive lipids. Thereby, acts as a central switch between the signaling pathways activated by these second messengers with different cellular targets and opposite effects in numerous biological processes (By similarity). Has no apparent specificity with regard to the acyl compositions of diacylglycerol. Specifically expressed in the cerebellum where it controls the level of diacylglycerol which in turn regulates the activity of protein kinase C gamma. Through protein kinase C gamma, indirectly regulates the dendritic development of Purkinje cells, cerebellar long term depression and ultimately cerebellar motor coordination (By similarity).
Synonyms: DGK-gamma; DAGK3
Tractability: Antibody: its Gene Ontology location is reachable by antibodies, with high confidence; the Human Protein Atlas places it where antibodies can reach. PROTAC: a small molecule that binds it is known.
Target class: Enzyme; Transferase
Gene: Protein-coding gene on chromosome 3 (186,105,668 to 186,362,261, reverse strand). Ensembl gene ENSG00000058866.
Subcellular location: Membrane; Cytoplasm, cytosol; Cytoplasm, cytoskeleton
Subcellular location (Human Protein Atlas): Plasma membrane; Vesicles
Pathways (Reactome):
Hemostasis: Effects of PIP2 hydrolysis
Gene Ontology:
Molecular function: ATP-dependent diacylglycerol kinase activity; lipid binding; calcium ion binding; kinase activity
Biological process: diacylglycerol metabolic process; glycerolipid metabolic process; lipid phosphorylation; phosphatidic acid biosynthetic process; intracellular signal transduction; negative regulation of phospholipase C/protein kinase C signal transduction; platelet activation; phospholipase C-activating G protein-coupled receptor signaling pathway; regulation of dendrite development; signal transduction
Cellular component: cytosol; membrane; plasma membrane; cytoskeleton
Genetic constraint (gnomAD): Loss-of-function variants: 63 observed, 84.94 expected, observed/expected ratio (o/e) 0.74, 90% interval 0.61 to 0.92. The upper end of that interval is the gene's LOEUF score, 0.92, which puts it in group 3 of 6, group 1 being the genes least tolerant of losing a copy. Missense variants: 821 observed, 922.93 expected, observed/expected ratio (o/e) 0.89, 90% interval 0.84 to 0.94. Synonymous variants: 300 observed, 334.38 expected, observed/expected ratio (o/e) 0.9, 90% interval 0.82 to 0.99.
Homologues: Orthologues: chimpanzee DGKG (99% identical), macaque DGKG (98% identical), dog DGKG (94% identical), pig DGKG (93% identical), rabbit DGKG (92% identical), guinea pig DGKG (92% identical), mouse Dgkg (89% identical), rat Dgkg (88% identical), zebrafish dgkg (65% identical), Drosophila melanogaster CG34384 (29% identical), Drosophila melanogaster rdgA (26% identical), Caenorhabditis elegans dgk-4 (23% identical), and 1 more. Paralogues in human: DGKB (63% identical), DGKA (52% identical), DGKD (30% identical), DGKH (30% identical), DGKK (26% identical), DGKQ (26% identical), DGKZ (26% identical), DGKI (25% identical), DGKE (23% identical).
Diseases named in the same sentence as DGKG in open-access papers:
DGKG is named in the same sentence as 23 diseases in open-access papers, as found by Europe PMC text mining. Sharing a sentence is not in itself a finding about the gene and the disease. The quoted sentences say what the papers report.
Obesity (7 papers, 2010 to 2025). Accumulation of substantial excess body fat. "We found the SNP rs1516725, in the region of DGKG, which is associated with obesity in GWAS catalog, being mapped to the volume of grey matter in right ventral striatum (P<10−26)." (PMID 40917653, 2025). "The diacylglycerol kinase gamma (DGKG) gene was additionally found upregulated in AN neurons, which has previously been associated with obesity and chronic stress, suggesting it may potentially play a role in the development of AN." (PMID 32377792, 2020).
colorectal cancer (2 papers, 2020 to 2023). A primary or metastatic malignant neoplasm that affects the colon or rectum. "Another gene, encoding diacylglycerol kinase gamma (DGKG) was associated with aging and it was dysregulated in colorectal cancer through DNA hypermethylation." (PMID 37199585, 2023). "Meanwhile, in colorectal cancer (CRC), DGKγ plays tumor-suppressive roles, while DGKζ activity promotes tumor progression." (PMID 32722576, 2020). "For instance, DGKγ expression is downregulated in HCC tumor tissues and colorectal cancer (CRC) cell lines when compared to non-tumor control tissues, and this correlates with poor clinical outcomes." (PMID 32722576, 2020).
hepatocellular carcinoma (2 papers, 2024 to 2025). A malignant tumor that arises from hepatocytes. "Recently, DGKγ has also been implicated in tumor angiogenesis and the differentiation of immunosuppressive regulatory T cells in hepatocellular carcinoma (HCC)." (PMID 39684917, 2024). "However, the inhibition of DGKG expression in hepatic ECs has been shown to reduce TGF-β1 secretion in the liver, thereby decreasing angiogenesis and immune evasion in hepatocellular carcinoma (HCC)." (PMID 40114970, 2025).
migraine (2 papers, 2023 to 2025). "Additionally, it appears that methylation of the DGKG gene, which encodes diacylglycerol kinase gamma, is closely associated with migraine pathogenesis, although limited evidence currently exists to evaluate the clinical relevance of epigenetic alterations in this gene." (PMID 40391079, 2025). "A candidate gene for which methylation is closely related to the pathophysiology of migraine is DGKG, but there are currently insufficient data to assess the clinical relevance of epigenetic changes in this gene." (PMID 37298078, 2023).
acute lymphoblastic leukemia (1 paper, 2024). Leukemia with an acute onset, characterized by the presence of lymphoblasts in the bone marrow and the peripheral blood. "Molecular docking showed that dasatinib, a small molecule tyrosine kinase inhibitor used in the treatment of chronic lymphocytic and acute lymphoblastic leukemia, could target DGKG." (PMID 39217365, 2024).
acute myeloid leukemia (1 paper, 2023). Acute myeloid leukemia (AML) is a group of neoplasms arising from precursor cells committed to the myeloid cell-line differentiation. "According to cancer expression databases, acute myeloid leukemia (AML) exhibits significant overexpression of multiple DGK isoforms, including DGKA, DGKD and DGKG, without a precise correlation with specific AML subtypes." (PMID 37509516, 2023).
Alzheimer disease (1 paper, 2022). A progressive, neurodegenerative disease characterized by loss of function and death of nerve cells in several areas of the brain leading to loss of cognitive function such as memory and language. "Further validation was performed in another expression profile of AD, GSE33000, and the result implied high sensitivity and specificity of DGKG, MAP3K7IP2, NFKBIE, VIP, and PCCB for diagnosing Alzheimer’s disease (combined AUC = 0.9388)." (PMID 36092935, 2022).
Anxiety (1 paper, 2023). Intense feelings of nervousness, tension, or panic often arise in response to interpersonal stresses. "The diacylglycerol kinase gamma gene (DGKG) was reported to be negatively regulated by the triiodothyronine hormone in mice inactivated for astrocyte-specific Dio2, which resulted in mood and behavioral disorders, such as anxiety-depressive behavior." (PMID 36658485, 2023).
Ataxia (1 paper, 2022). Ataxia refers to impaired coordination of voluntary muscle movement. "The genes in Group E belong to the phosphatidylinositol signaling system (KEGG pathway mmu04070); Dgkg↓ (diacylglycerol kinase γ) encoding DGKγ was significantly downregulated in both Homo and Het, and is known to be associated with ataxia." (PMID 36011327, 2022).
Cognitive impairment (1 paper, 2022). Abnormal cognition is characterized by deficits in thinking, reasoning, or remembering. "Considering the potentially critical role of the cerebellum in cognitive impairment of AD, how DGKG participates in AD warrants further research." (PMID 36092935, 2022).
colon cancer (1 paper, 2024). "We used non-tumoral colon and colon cancer cell line CACO2 as DGKG promoter methylation controls." (PMID 39217365, 2024).
glaucoma (1 paper, 2018). Increased pressure in the eyeball due to obstruction of the outflow of aqueous humor. "We also investigated 9 novel glaucoma-associated loci from UKB in GERA, and 6 of the novel loci replicated at Bonferroni significance (near IKZF2, CADM2, near DGKG, ANKH, EXOC2, and LMX1B)." (PMID 29891935, 2018).
glioma (1 paper, 2025). A benign or malignant brain and spinal cord tumor that arises from glial cells (astrocytes, oligodendrocytes, ependymal cells). "The expression levels of DGKG mRNA and protein were detected in several glioma cells and the results demonstrated that DGKG was expressed in glioma cells, especially in radiotherapy-resistant T98G cells." (PMID 40296900, 2025).
heart failure (1 paper, 2011). Inability of the heart to pump blood at an adequate rate to meet tissue metabolic requirements. "Although no changes were detected in the expression level of DGKγ in failing heart, we suspected that DGKγ might be activated and might contribute to the process of progressive heart failure." (PMID 21548979, 2011).
oral cancer (1 paper, 2025). "In order to examine the impact of DGKG on the proliferative capacity of oral cancer cells, CCK8 assay and colony formation assay were utilized for assessment." (PMID 40887599, 2025).
tumor (16 papers, 2012 to 2026). "DGKγ instead plays a crucial role in the tumor microenvironment of hepatocellular carcinoma, because its increased expression, associated with the hypoxic conditions in tumor vascular endothelial cells, correlates with a poorer prognosis." (PMID 40859612, 2026). "Evidence suggests that hypoxia induces the overexpression of diacylglycerol kinase γ (DGKG) in tumor endothelial cells, which then activates the ZEB2/TGF-β1 axis, promoting angiogenesis and immune suppression in HCC." (PMID 39849606, 2025). "For instance, diacylglycerol kinase gamma (DGKG) in tumor endothelial cells (ECs) has been shown to promote HCC progression, suggesting its potential as a therapeutic target." (PMID 39857819, 2025). "Hypoxia in the TME can induce high levels of diacylglycerol kinase gamma in tumor vascular endothelial cells, which in turn can promote tumor angiogenesis and immune evasion in hepatocellular carcinoma through the ZEB2/TGF-β1 axis." (PMID 39588373, 2024). "In fact, GLUT1 expression is high in HCC and promotes tumorigenicity, therefore DGKγ plays tumor suppressor roles in HCC by lowering GLUT1 levels." (PMID 32722576, 2020). "DGKγ also plays tumor suppressor roles in HCC cells by reducing cell migration when DGKγ is overexpressed." (PMID 32722576, 2020). "Taken together, these results suggest that DGKG influences tumor growth through mechanisms beyond cell proliferation, including the promotion of EMT, enhancement of migration and invasion, modulation of lipid metabolism, and engagement of oncogenic signaling pathways." (PMID 40887599, 2025). "Furthermore, in vivo, orthotropic GBM animal models analysis showed that the tumor volumes were much smaller in the DGKG knockdown group." (PMID 40296900, 2025). "DGKγ has been reported to function as a tumor suppressor by inhibiting cell migration." (PMID 39463203, 2024). "As previously stated, DGKγ plays tumor-suppressive roles in CRC." (PMID 32722576, 2020). "A recent study also suggests that DGKG is a tumor suppressor in colorectal cancer." (PMID 31097707, 2019). "Interestingly, DGKγ may have tumor‐suppressive properties in colorectal cancer and is associated with a more favorable prognosis for acute myeloid leukemia, highlighting its tumor‐specific role." (PMID 40859612, 2026). "Due to the potential role of DGKG in PitNET biology, we decided to perform drug-gene interaction analysis to find potential drugs that could be repurposed as alternative therapies for these neoplasms." (PMID 39217365, 2024). "Thus, opposite to the tumor-suppressive roles of DGKγ DGKζ may also promote tumorigenesis by potentiating cell invasion and migration in several cancer types by regulating Rac1 and RhoA activity." (PMID 32722576, 2020). "Diacylglycerol kinase gamma (DGKG), specifically hyper-expressed in tumor vascular ECs of HCC, promotes tumor angiogenesis and facilitates the formation of an immunosuppressive microenvironment under hypoxia." (PMID 40248695, 2025). "In tumor vascular endothelial cells (ECs), under hypoxic conditions, HIF-1α activates the transcription of diacylglycerol kinase gamma (DGKG)." (PMID 39223632, 2024). "Using healthy donor CD34+ cells as a reference, we detected overexpression of DGKA, DGKG, DGKD and DGKQ in tumor samples, while DGKH and DGKZ were unchanged." (PMID 37509516, 2023). "DGKG recruits USP16 to deubiquitinate ZEB2, maintaining its stability, resulting in increased secretion of TGF-β1, driving the differentiation of Tregs, and promoting tumor immune evasion." (PMID 39223632, 2024). "To further explore whether DGKG may influence tumor progression via mechanisms independent of proliferation, we performed correlation analyses using TCGA expression data." (PMID 40887599, 2025).
tumor (continued). "Targeting DGKG can enhance the efficacy of dual blockade of PD-1 and VEGFR-2 therapies.Therefore, besides direct tumor-killing strategies, attempting to inhibit tumor growth by targeting tumor angiogenesis might be a more moderate, effective, and less resistance-prone approach." (PMID 39849606, 2025).
cancer (3 papers, 2021 to 2026). A tumor composed of atypical neoplastic, often pleomorphic cells that invade other tissues. "Among the 54 cancer-related genes, DGKG, MPND, NPIPB5, PRR21, SGSM1, and TRIM67 displayed frameshift mutations." (PMID 34104084, 2021). "This suggests that the protective role of DGKG may also involve the removal of cellular DAG in addition to its reported role in modulating glucose import in cancer cells." (PMID 37509516, 2023). "In addition, the present study revealed 6 cancer-related genes, DGKG, MPND, NPIPB5, PRR21, SGSM1, and TRIM67, which showed novel frameshift mutations." (PMID 34104084, 2021).
DGKG also shares sentences with these, for which no sentence is quoted: breast carcinoma (1 paper); diabetes (1); glioblastoma (1); HIV-1 infection (1); lung carcinoma (1); ocular hypertension (1).